TIPE1 (TNF alpha induced protein 8 like 1)
Diseases named in the same sentence as TIPE1 in open-access papers (continued):
Sharing a sentence is not in itself a finding about the gene and the disease.
atherosclerosis (1 paper, 2024). A disease characterized by the build-up of fatty material and calcium deposition in the arterial wall resulting in partial or complete occlusion of the arterial lumen. "In vascular endothelial cells, the up-regulation of TIPE1 resulted in an increase in reactive oxygen species (ROS)-induced oxidative stress, leading to apoptotic cell death and the progression of atherosclerosis." (PMID 38216955, 2024). "Specifically, the study focused on the involvement of TIPE1 (Tumor necrosis factor-α-induced protein 8-like 1, TNFAIP8L1), a recently discovered member of the TIPE protein family known to contribute to inflammation, endothelial dysfunction, and atherosclerosis." (PMID 38216955, 2024). "TIPE1, a member of the TNFAIP8 family, has been reported to play a crucial role in various cellular processes including cell death, inflammation, endothelial dysfunction, and atherosclerosis." (PMID 38216955, 2024).
bladder cancer (1 paper, 2022). "Furthermore, TIPE1 was also lower in breast and bladder cancer than in malignant lymphomas." (PMID 36118167, 2022).
breast tumor (1 paper, 2019). "The effect of TIPE1 on tumor growth was further explored in nude mice with human breast tumor xenografts." (PMID 31179241, 2019). "Thus, our results show that TIPE1 exhibits significant inhibitory effect on breast tumor xenografts." (PMID 31179241, 2019).
diffuse large B-cell lymphoma (1 paper, 2022). "Here we observed TIPE1 expression in diffuse large B cell lymphoma (DLBCL)." (PMID 36118167, 2022).
Glucose intolerance (1 paper, 2024). Glucose intolerance (GI) can be defined as dysglycemia that comprises both prediabetes and diabetes. "Tipe1 deletion in db/db mice led to higher random and fasting blood glucose levels, lower fasting insulin levels, and severe glucose intolerance compared to Ins2‐Cre‐db/db mice." (PMID 38417114, 2024).
invasive breast carcinoma (1 paper, 2022). A carcinoma that infiltrates the breast parenchyma. "The GEPIA and TIMER analyses revealed that TIPE1 was upregulated in DLBCL tissues but not in invasive breast carcinoma, urothelial bladder carcinoma, or liver hepatocellular carcinoma tissues." (PMID 36118167, 2022).
liver cancer (1 paper, 2018). An epithelial or non-epithelial malignant neoplasm that arises from the liver. "TIPE1 interacts with Rac1, inhibits p65 and c-Jun N-terminal kinase, and induces caspase-mediated cellular apoptosis in liver cancer cells." (PMID 30586922, 2018).
lymphadenitis (1 paper, 2022). Acute or chronic inflammation of one or more lymph nodes. "In the immunohistochemical experiments, the expression of TIPE1 was higher in malignant lymphomas than in lymphadenitis." (PMID 36118167, 2022). "Interestingly, TIPE1 expression from HL and NHL tissues was higher than in lymphadenitis samples." (PMID 36118167, 2022).
lymphoma (1 paper, 2022). A malignant (clonal) proliferation of B- lymphocytes or T- lymphocytes which involves the lymph nodes, bone marrow and/or extranodal sites. "Overall, our findings suggest that TIPE1 expression is upregulated in malignant lymphomas." (PMID 36118167, 2022). "Although previous studies demonstrated that TIPE1 might play different roles in different tumors, its expression and role in lymphoma are unclear." (PMID 36118167, 2022). "The expression and potential role of TIPE1 in the development of lymphoma remain unclear." (PMID 36118167, 2022).
renal carcinoma (1 paper, 2022). A carcinoma arising from the epithelium of the renal parenchyma or the renal pelvis. "Although TIPE1 may be a prognostic marker in renal cancer, TIPE1 is typically expressed in a variety of human tumor tissues with low cancer specificity (HPA database)." (PMID 36118167, 2022).
virus infection (1 paper, 2020). "Another study has shown that the expression of TIPE1 was upregulated in virus infection-related cancer cell lines." (PMID 33520705, 2020). "Therefore, we believe that TIPE1 may play a unique biological role in virus infection-related tumors." (PMID 33520705, 2020).
cancer (15 papers, 2013 to 2025). A tumor composed of atypical neoplastic, often pleomorphic cells that invade other tissues. "Members of this family are expressed in various human cancer cell lines, with TIPE1 being particularly significant in secretion and carcinogenesis." (PMID 40343258, 2025). "To date, there have been only a few articles about the role of TIPE1 in tumorigenesis, and its biological functions in cancers remain controversial." (PMID 36151091, 2022). "Previous studies have shown that TIPE1 can inhibit cell growth and induce cell death in several types of cancer." (PMID 33520705, 2020). "Recent studies have shown that tumour necrosis factor‐α–induced protein 8 like‐1(TIPE1) plays distinct roles in different cancers." (PMID 32588529, 2020). "Functionally, TIPE1 inhibits cancer cell proliferation preferentially by downregulating ERK phosphorylation." (PMID 31179241, 2019). "The reduction of TIPE1 in poorly cohesive carcinoma was further confirmed by immunohistochemical staining and Western blot analyses." (PMID 28994231, 2018). "We will put our efforts to determine the potential direct target of TIPE1 in regulating NSCLC cancer cell behaviors." (PMID 29108244, 2017). "Recent studies had suggested that TIPE1 may play a significant role in cancer development and progression." (PMID 34188681, 2021). "A recent study reported that TIPE1 could inhibit cancer cells by induing apoptosis, and our studies came to the same conclusion." (PMID 34188681, 2021). "The results showed that TIPE1 mRNA was lower in cancer tissues." (PMID 34188681, 2021). "TIPE1 was mostly found to be antitumorigenic, and downregulated in most cancers." (PMID 33520705, 2020). "Interestingly, our results showed that the expression of TIPE1 in the ER-positive cell line (MCF-7) was significantly higher than that in the other cancer cells." (PMID 31179241, 2019). "The mechanism leading to the downregulated of TIPE1 expression in several cancer was still unclear." (PMID 29108244, 2017). "Meanwhile, a wound-healing assay was used to evaluate the effect of TIPE1 on cancer cell migration." (PMID 29108244, 2017). "In addition, TIPE1 was also expressed in various tissues of mice, including brain, liver, kidney, stomach and so on, and it was up-regulated in various carcinoma cell lines, especially the cell lines transformed with virus." (PMID 26207809, 2015). "High level of TIPE1 mRNA is detected in most human carcinoma cell lines, which suggests that it may play a role in carcinogenesis." (PMID 25946186, 2015). "TIPE1 is supposed that it may play role in carcinogenesis for a high level of TIPE1 mRNA is detected in most human carcinoma cell lines." (PMID 24274578, 2013). "In addition, TIPE1 seems to act opposite functions in different cancers." (PMID 34188681, 2021). "Most reports believe that TNFAIP8 and TIPE3 have antiapoptotic and tumorigenesis effects, while TIPE1 and TIPE2 have pro-apoptotic and antitumor effects in most cancers." (PMID 34925463, 2021). "Adenovirus-directed expression of TIPE2 suppresses gastric cancer growth by induction of apoptosis and inhibition of AKT and ERK1/2 signaling, suggesting that, similar to TIPE1, TIPE2 mostly inhibits various cancer cell growths by the induction of apoptosis." (PMID 30586922, 2018). "It was found that the level of TIPE1 and TIPE3 was decreased in poorly cohesive carcinoma compared with adjacent non‐tumour tissue." (PMID 28994231, 2018). "Furthermore, the expression of TIPE1 in MCF-7 cells, which possess low proliferation potential, was significantly higher than that in the other cancer cells." (PMID 31179241, 2019). "Recent studies have shown that the downregulation of TIPE1 is positively correlated with patient survival in HCC, and it serves as a novel prognostic indicator by reducing cell growth and metastasis in several cancers." (PMID 31179241, 2019).
cancer (continued). "Unlike TIPE2, TIPE1 is expressed in various mouse tissues except for mature B and T lymphocytes and in most human carcinoma cell lines." (PMID 31179241, 2019). "Moreover, TIPE1 mRNA and protein expression was undetectable or low level in all NSCLS cancer cell lines." (PMID 29108244, 2017).
tumor (13 papers, 2015 to 2022). "More importantly, TIPE1 more significantly offset the reduction in tumor volume caused by chemotherapy drugs." (PMID 33520705, 2020). "In hepatocellular carcinoma, TIPE1 is downregulated and associated with Tumor Node Metastasis (TNM) staging and patient death." (PMID 30586922, 2018). "The results of an in vivo tumorigenesis experiment in nude mice showed that the nude mice injected with MNNG/HOS Cl #5 cells transfected with TIPE1 formed tumor with significantly smaller volumes and weights than the controls." (PMID 36151091, 2022). "Consistently, the average tumor weight of lentivirus-TIPE1 group at the time of killing was noticeably less than that of control group." (PMID 34188681, 2021). "Recent studies also revealed that TIPE1 probably serves as a tumor suppressor gene in several tumor types." (PMID 33520705, 2020). "Immunohistochemical analysis showed that the expression of LC3B in tumour tissue was reduced in the Lv‐TIPE1 group compared to that observed in the Lv‐control group, whereas the expression of pS6 was increased." (PMID 32588529, 2020). "In this study, the decreased density of characteristic autophagosomes and the decreased expression of LC3B in tumour tissue sections provided strong evidence that autophagy was inhibited after TIPE1 was overexpressed." (PMID 32588529, 2020). "Our in vivo experiments showed that TIPE1 significantly reduced both tumor volume and weight compared to controls." (PMID 31179241, 2019). "TIPE1, which acts as a cell death regulator, has emerged as a tumor suppressor in the process of carcinogenesis." (PMID 31179241, 2019). "We injected BGC823 cells and SGC7901 cells infected with lentivirus‐TIPE1 into the tail vein of nude mice and examined their internal organs for tumours seeding." (PMID 28994231, 2018). "Evaluated by qRT-PCR and immunohistochemical staining, lower TIPE1 mRNA and protein expression was found in the lung tumor tissue, compared with adjacent non-tumor tissues, which positively correlated with tumor patient survival." (PMID 29108244, 2017). "NSCLC tumor microarray by us also demonstrated that the patients with low TIPE1 expression have dramatically shorter survival than those with high TIPE1 expression." (PMID 29108244, 2017). "TIPE1 expression in HCC tissues positively correlated with tumor pathologic grades and patient survival." (PMID 29108244, 2017). "In conclusion, in the present study we showed that TIPE1 expression was dramatically decreased in the lung tumor tissues, and positively correlated with tumor patient survival." (PMID 29108244, 2017). "Overexpression of TIPE1 significantly diminished tumor growth and cell growth, companied with proliferation inhibition and apoptosis induction in vivo and in vitro, due to TIPE1-regulated protein expression." (PMID 29108244, 2017). "Importantly, the TIPE1 levels were higher in the group with a tumor size <5 cm than in the group with a tumor size ≥5 cm." (PMID 36151091, 2022). "As the autonomous autophagy of tumor cell may also promote tumor growth, we speculate that the higher expression of TIPE1 in DLBCL may contribute to the autophagy of tumor cells, thereby causing tumor growth of DLBCL." (PMID 36118167, 2022). "Using the TIMER platform, we found that TIPE1 expression in DLBCL was predicted to correlate with MKI67 expression, whether the association was adjusted by tumor purity (p < 0.05) or age (p < 0.05)." (PMID 36118167, 2022). "As MKI67 is a protein associated with cell proliferation, these results suggest that TIPE1 expression in DLBCL may contribute to tumor growth." (PMID 36118167, 2022). "In addition, according to the data from GEPIA2, TNFAIP8 expression was upregulated in DLBCL tumor (n = 47, p < 0.05), similar to that of TIPE1." (PMID 36118167, 2022). "Tumor growth curve showed that TIPE1 significantly inhibited the growth of SKOV3 xenograft." (PMID 34188681, 2021).
tumor (continued). "Previous studies have revealed that TIPE1 serves as a tumor suppressor gene in several tumor types." (PMID 33520705, 2020). "Importantly, TIPE1 dramatically restrained the expression and activities of MMP2 and MMP9 which are demonstrated to promote tumour progression and are implicated in EMT." (PMID 28994231, 2018). "Overall, TIPE1’s high expression levels in DLBCL may contribute to tumor growth in DLBCL." (PMID 36118167, 2022). "Furthermore, cell biology assays confirmed that overexpression of TIPE1 could inhibit tumor cell growth and migration." (PMID 34188681, 2021). "In addition, TIPE1 promoted tumour growth in BALB/c nude mice." (PMID 32588529, 2020). "Of these genes, TNFAIP8, TIPE1, and TIPE3 are known to greatly influence tumor occurrence and development, while TIPE2 is mainly involved in innate immunity and acquired immunity." (PMID 36118167, 2022). "Furthermore, we investigated whether TIPE1 arrested tumor xenograft growth in vivo." (PMID 34188681, 2021). "TIPE1 A549 cells and Ctrl cells engrafted onto 10 BALB/c nude mice (5 mice per group) to monitor tumor growth." (PMID 29108244, 2017). "Thus, we next investigate whether TIPE1 arrests tumor xenograft growth in vivo." (PMID 29108244, 2017). "Unlike the other members, TIPE1 seemed to play more complicated roles in different tumor progressions." (PMID 34188681, 2021). "Not surprisingly, TIPE1 has a significant negative correlation with p-ERK in mouse tumor tissues and clinical specimens." (PMID 31179241, 2019). "qPCR results indicated that TIPE1 mRNA was 8.5-fold lower in tumor tissues than in nontumor tissues." (PMID 29108244, 2017). "In conclusion, TIPE1 is highly expressed in DLBCL and may contribute to tumor growth in DLBCL." (PMID 36118167, 2022). "Not surprisingly, TIPE1 showed a negative correlation with p-ERK in clinical specimens and mouse tumor tissues." (PMID 31179241, 2019).
infection (2 papers, 2019 to 2020). The state of being infected such as from the introduction of a foreign agent such as serum, vaccine, antigenic substance or organism. "In addition, knocking down TIPE1 expression with Sh‐TIPE1 infection significantly decreased cell proliferation and decelerated cell cycle progression in CNE‐2Z cells." (PMID 32588529, 2020).
TIPE1 also shares sentences with these, for which no sentence is quoted: COVID-19 (2 papers); clear cell renal cell carcinoma (1); colon cancer (1); dementia (1); endothelial dysfunction (1); gynecological cancer (1); Hepatic steatosis (1); idiopathic interstitial pneumonia (1); nonalcoholic steatohepatitis (1); skin cancer (1); tongue cancer (1); Tumor Metastasis (1); type 2 diabetes mellitus (1); urothelial bladder carcinoma (1).